GBA1 (glucosylceramidase beta 1)
Diseases named in the same sentence as GBA1 in open-access papers (continued):
Sharing a sentence is not in itself a finding about the gene and the disease.
Gaucher disease (continued). "Gaucher disease is a rare, genetic, hereditary disease in which mutations occur in the GBA1 gene, which codifies the GCase enzyme." (PMID 39767201, 2024). "Biallelic loss-of-function mutations in GBA1 cause Gaucher disease (GD), the most common lysosomal storage disorder (LSD)." (PMID 38712038, 2024). "Gaucher disease (GD) is caused by glucocerebrosidase (GBA1) deficiency, leading to skeletal complications." (PMID 38575988, 2024). "Gaucher disease (GD) is a lysosomal storage disorder with accumulation of GlcCer due to mutations in the lysosomal glucocerebrosidase (GBA1) gene." (PMID 38280458, 2024). "Gaucher disease (GD) is a recessively inherited lysosomal storage disorder characterized by a deficiency of lysosomal glucocerebrosidase (GBA1)." (PMID 38072450, 2024). "Just like many other GBA1 variants, the pathogenic variant GBA1 p.V433L is commonly associated with PD and Gaucher’s disease, although reports on the National Center for Biotechnology Information dbSNP database are outdated and limited." (PMID 38191580, 2024). "Homozygotes or combined heterozygote carriers of GBA1 mutations result in Gaucher’s Disease (GB), a lysosomal storage disorder with an autosomal recessive form of inheritance." (PMID 39766872, 2024). "Gaucher disease (GD) is an autosomal recessive lysosomal storage disease caused by pathogenic variations in the GBA1 gene." (PMID 38553911, 2024). "A link between GBA1 mutations and Ox stress is further supported by observations in humans, in PD and Gaucher disease patients." (PMID 39663354, 2024). "We screened GBA1 for rare pathogenic Gaucher disease (GD)-causing variants and common PD risk variants." (PMID 39420034, 2024). "GBA1 encodes the lysosomal enzyme glucocerebrosidase (Gcase), which is deficient in Gaucher disease." (PMID 38773124, 2024). "Homozygous GBA1 variants, including the p.T75del and c.115+1G>A mutations have been reported to cause Gaucher disease." (PMID 39606324, 2024). "Several variants in GBA1, such as p.F298L, p.V230G, p.W223R, and p.P198L, have been previously reported in Gaucher disease patients." (PMID 39606324, 2024). "The human GBA1 gene encodes lysosomal acid β-glucocerebrosidase, whose activity is deficient in Gaucher disease (GD)." (PMID 39404383, 2024). "Gaucher disease (GD) is a lysosomal storage disorder arising from an inherited loss in activity of the lysosomal hydrolase glucosylceramidase beta 1 GBA1." (PMID 39490443, 2024). "Gaucher disease (GD) is a lysosomal storage disorder caused by a mutation in the GBA1 gene, responsible for encoding the enzyme Glucocerebrosidase (GCase)." (PMID 38649404, 2024). "GBA1 mutations cause the lysosomal storage disorder Gaucher disease (GD) and are the commonest known genetic risk factor for PD." (PMID 38368939, 2024). "Gaucher disease (GD) is a lysosomal lipid storage disorder caused by β-glucocerebrosidase (encoded by GBA1 gene) activity deficiency, resulting in the accumulation of glucosylceramide (Gb1) and its deacylated metabolite glucosylsphingosine (lyso-Gb1)." (PMID 39596090, 2024). "GCase deficiency causes Gaucher Disease (GD), which is mainly due to biallelic pathogenetic variants in the GCase-encoding gene, GBA1." (PMID 38928321, 2024). "Mutations in GBA1 cause Gaucher disease and are the most important genetic risk factor for Parkinson’s disease." (PMID 38924406, 2024). "In the Greek population, two ethnic cohorts of individuals with sporadic PD were screened for eight distinct GBA1 pathogenic variants, which account for 87% of the variants found in Gaucher disease patients diagnosed in Greece." (PMID 39766872, 2024). "Gaucher disease is a rare, inherited metabolic disorder in which deficiency of GBA1 results in glucosylceramide accumulation throughout the body, particularly in the bone marrow, spleen, and liver." (PMID 39115943, 2024). "We observed two common variants p.Leu483Pro and p.Ala487Thr in the GBA1 gene in 23% of Indian patients with adult Gaucher disease." (PMID 38444573, 2024).
Gaucher disease (continued). "Genetic variants of GBA1 can cause the lysosomal storage disorder Gaucher disease and are among the highest genetic risk factors for Parkinson's disease (PD)." (PMID 38666485, 2024). "The detrimental effect of GBA1 mutations on cognition was observed only in cases harbouring severe mutations (i.e., pathogenic mutations associated with neuronopathic forms of Gaucher disease), again corroborating previous studies." (PMID 39420034, 2024). "The first indication of a link between parkinsonism and GBA1 mutations stems from observations of PD in patients with Gaucher disease and in their relatives that were carriers." (PMID 38773124, 2024). "Biallelic mutation of GBA1 causes Gaucher disease, while heterozygote carriers of the GBA1 mutation are estimated to have a more than five-fold increased risk of developing PD, which makes alteration of this gene the most important genetic risk factor." (PMID 39335634, 2024). "Only the non-Gaucher disease causing GBA1 PD risk variant E326K, of the known PD risk variants, was associated with mortality in PD." (PMID 38849413, 2024). "Gaucher disease (GD) is a rare autosomal recessive condition characterized by a deficiency of the lysosomal enzyme beta-glucocerebrosidase (GBA1)." (PMID 38365689, 2024). "Gaucher disease (GD) is a lysosomal storage disorder stemming from biallelic mutations in GBA1, characterized by glucocerebrosidase dysfunction and glucocerebroside and glucosylsphingosine accumulation." (PMID 38339105, 2024). "Pathogenic mutations of ß-glucocerebrosidase enzyme coding gene (GBA1) lead to Gaucher disease (GD) when inherited in the biallelic pattern." (PMID 38153678, 2024). "Gaucher disease (GD) is a rare hereditary disease caused by mutations in the GBA1 gene, which encodes the enzyme glucocerebrosidase, resulting in a deficiency in this enzyme." (PMID 38540192, 2024). "Gaucher disease, the inherited deficiency of glucocerebrosidase, is caused by biallelic loss-of-function mutations in the gene GBA1, which is also the most frequent genetic risk factor for Parkinson’s disease." (PMID 39388267, 2024). "Homozygous or compound heterozygous GBA1 mutations cause the lysosomal storage disease Gaucher disease (GD), due to severe loss of GCase activity." (PMID 38329128, 2024). "Gaucher disease (GD) is a rare, autosomal recessive, metabolic disorder caused by pathological variants in the GBA1 gene leading to deficiency in the activity of the lysosomal enzyme glucocerebrosidase." (PMID 38792468, 2024). "To conclude, our study shows that human GBA1, deficient in Gaucher disease, can remove 6-O-acyl-Glc from 4-methylumbelliferone as well as from cholesterol and plant-derived campesterol and sitosterol." (PMID 39395789, 2024). "The GBA1 gene encodes the enzyme lysosomal hydrolase glucocerebrosidase (GCase), whose deficiency causes Gaucher’s disease." (PMID 39596436, 2024). "Biallelic GBA1 variants cause Gaucher disease, a lysosomal storage disorder that leads to a variety of clinical presentations." (PMID 39668204, 2024). "Of note, homozygous GBA1 variants cause Gaucher’s disease, a common LSD, while heterozygous GBA1 variant carrier status increases risk for PD." (PMID 39724071, 2024). "Gaucher disease (GD) is an autosomal recessive disorder due to mutations in GBA1 encoding lysosomal glucocerebrosidase." (PMID 38974840, 2024). "Biallelic mutations in GBA1 result in decreased GCase activity causing Gaucher disease (GD) with glycosphingolipid excess in the brain and soma." (PMID 38924406, 2024). "In summary, five of the 499 (AF: 0.005) MSA cases were carriers of GBA1 variants pathogenic for Gaucher disease." (PMID 39020124, 2024). "The GBA1 gene, which encodes the lysosomal enzyme glucocerebrosidase (GCase) and whose homozygous mutations cause Gaucher disease, is recognized as the strongest genetic risk factor for sPD." (PMID 39201619, 2024).
Gaucher disease (continued). "Biallelic mutations in the glucosylceramidase beta 1 (GBA1) gene cause Gaucher’s disease (GD), an autosomal recessive disease and the most prevalent lysosomal storage disorder (LSD)." (PMID 39795868, 2024). "The other GBA1 variants (p.D179H, p.R296Q, and p.R502C) are all associated with Gaucher disease in a bi-allelic state and were robustly associated with PD in this study." (PMID 38191580, 2024). "GBA1 product catalyzes the hydrolysis of glucosylceramides into free ceramides and glucose in the lysosome, and it is associated with Gaucher’s disease type I and II (GD), Parkinson’s disease (PD) and dementia with Lewy bodies (DLB)." (PMID 36768367, 2023). "Biallelic mutations in the glucocerebrosidase (GBA1) gene cause Gaucher disease, characterized by lysosomal accumulation of glucosylceramide and glucosylsphingosine in macrophages." (PMID 36745788, 2023). "Gaucher disease (GD) is caused by biallelic pathogenic variants in the acid β-glucosidase gene (GBA1), leading to a deficiency in the β-glucocerebrosidase (GCase) enzyme activity resulting in the intracellular accumulation of sphingolipids." (PMID 37446383, 2023). "Gaucher disease (GD) is an autosomal recessively inherited disorder resulting from biallelic mutations in the gene GBA1 located on chromosome 1q21." (PMID 37986861, 2023). "The other GBA1 variants (p.S146L, p.D179H, p.R296Q and p.R502C) are all associated with Gaucher disease in a biallelic state and were robustly associated with PD in this study." (PMID 37090536, 2023). "Gaucher disease (GD) is the most frequent sphingolipidosis, caused by biallelic pathogenic variants in the GBA1 gene encoding for β-glucocerebrosidase (GCase, E.C. 3.2.1.45)." (PMID 37189391, 2023). "Mutations in the GBA1 gene cause Gaucher disease (GD), and are the greatest genetic risk factor for PD." (PMID 38127816, 2023). "GlcCer accumulation is also observed in flies that lack the fly homolog of GBA1, the gene that causes Gaucher disease." (PMID 36645408, 2023). "Gaucher disease results from mutations in the β-glucocerebrosidase 1 (GBA1) gene, which cause enzyme deficiency, leading to the accumulation of its substrate, glucosylceramide, in macrophages." (PMID 36835039, 2023). "Gaucher disease (GD) is a rare LSD caused by mutations in the GBA1 gene, which results in deficient lysosomal enzyme glucocerebrosidase (GCase) activity." (PMID 38248833, 2023). "Mutations in the acid β-glucocerebrosidase (GBA1) gene cause the lysosomal storage disease Gaucher’s disease (GD), which is an autosomal recessive condition that can present with both systemic and neurological symptoms." (PMID 37024507, 2023). "Mutations in GBA1, the gene encoding the lysosomal enzyme β-glucocerebrosidase (GCase), which cause Gaucher’s disease, are the most frequent genetic risk factor for Parkinson’s disease (PD)." (PMID 37024507, 2023). "Gaucher disease (GD) is one of the most common inherited lysosomal storage disorders (LSDs) and is caused by bi-allelic variants in the beta-glucocerebrosidase (GBA1) gene." (PMID 37685353, 2023). "Gaucher disease is a common lysosomal storage disorder in which recessive mutations in the β-glucocerebrosidase gene (GBA1) lead to a deficiency of lysosomal glucocerebrosidase activity." (PMID 36983221, 2023). "Gaucher disease (GD) is the most frequent sphingolipidosis, caused by biallelic pathogenic variants in the GBA1 gene." (PMID 37189391, 2023). "Biallelic GBA1 mutation causes Gaucher’s disease, mendelian disorders affecting several organs and tissues due to cells accumulating fatty substances." (PMID 37865674, 2023). "Here, using a zebrafish Gaucher disease model, we find that the mutation GBA1 N370S, predominant among Ashkenazi Jews, increases resistance to tuberculosis through the microbicidal activity of glucosylsphingosine in macrophage lysosomes." (PMID 36745788, 2023).
Gaucher disease (continued). "In 1996, C. Dunbar and D. Kohn published a detailed protocol for a clinical study involving 24 patients with Gaucher disease who were treated with a retroviral vector encoding the β-glucocerebrosidase 1 (GBA1) gene." (PMID 36835039, 2023). "There are more than 300 variants reported in the GBA1 gene known to be associated with Gaucher disease, of which L444P (c.1448T>C) is the most prevalent in India." (PMID 37383036, 2023). "Gaucher disease (GD) is a rare disease resulting from a deficiency in the lysosomal enzyme glucocerebrosidase (GCase) due to bi-allelic mutations in the GBA1 gene." (PMID 37893235, 2023). "Mutations in the GBA1 gene cause the lysosomal storage disorder Gaucher disease (GD) and are the greatest known genetic risk factors for Parkinson’s disease (PD)." (PMID 38127816, 2023). "Bi-allelic mutations in GBA1, the gene that encodes lysosomal β-glucocerebrosidase (GCase) cause Gaucher disease (GD), one of the most frequent lysosomal storage diseases." (PMID 36752535, 2023). "Gaucher Disease (GD), the most common lysosomal disorder, arises from mutations in the GBA1 gene and is characterized by a wide spectrum of phenotypes, ranging from mild hematological and visceral involvement to severe neurological disease." (PMID 37076591, 2023). "Bi-allelic mutations in the GBA1 gene are known to cause Gaucher disease (GD), whereas heterozygous mutations represent a major genetic risk factor for Parkinson’s disease (PD), conferring an approximately 20-fold increased risk." (PMID 38127816, 2023). "For instance, in neurons carrying the glucosylceramidase beta 1 (GBA1) mutations, characteristic of Gaucher's disease, mutant glucocerebrosidase considerably increases TFEB turnover, thereby impairing lysosomal biogenesis and worsening pathology." (PMID 37728021, 2023). "Biallelic mutations in GBA1 result in Gaucher disease (GD), the inherited deficiency of glucocerebrosidase." (PMID 37986861, 2023). "Gaucher disease (GD), the most prevalent lysosomal disorder, is caused by GBA1 gene mutations, leading to deficiency of glucocerebrosidase, and accumulation of glycosphingolipids in cells of the mononuclear phagocyte system." (PMID 37703870, 2023). "In a study that used cultured macrophages from 14 Gaucher’s disease patients and PD patients with mono-allelic GBA1 mutations, treatment of cultured macrophages with ambroxol augmented GCase activity in both patient groups." (PMID 36369100, 2022). "The mutation of GBA1 leading to Gaucher disease is associated with an increased incidence of cancer, and some evidence suggests that GBA1 is related to the pathogenesis of Parkinson’s disease." (PMID 35637196, 2022). "Mutations in GBA1 lead to Gaucher disease, which is characterized by neurological symptoms such dementia and ataxia, and treatment strategies include administration of recombinant human GBA." (PMID 36345044, 2022). "This is especially true for GBA1 variants and autosomal recessive PD variants, such as PRKN, that are potentially medically actionable given the reproductive implications and, in the case of GBA1, the association with Gaucher disease." (PMID 36446806, 2022). "Additional complexities are the need to consider copy number variants and recombinant alleles, reduced penetrance, and the association of GBA1 variants with Gaucher disease." (PMID 36446806, 2022). "β-GCase is encoded by the GBA1 gene, whose deficiency or dysfunction produces GlcCer accumulation, leading to the development of the lysosomal storage disease known as Gaucher’s disease." (PMID 35897658, 2022). "An observational study using an investigator-initiated registry followed off-label treatment with ambroxol of 38 patients with Gaucher’s disease and 3 PD patients with GBA1 mutations for a median duration of 19 months (median dose of 435 mg/day)." (PMID 36369100, 2022).
Gaucher disease (continued). "More than 495 mutations in the GBA1 gene are known to cause impairment in glycosphingolipid metabolism, and GBA1 mutation homozygosity leads to Gaucher’s disease (GD)." (PMID 36152140, 2022). "Gaucher disease (GD) is an autosomal recessive lysosomal storage disorder caused by mutations in the GBA1 gene, which produces the glucocerebrosidase (GCase) protein." (PMID 35711931, 2022). "Gaucher disease (GD) is an inherited disorder caused by recessive mutations in the GBA1 gene that encodes the lysosomal enzyme β-glucocerebrosidase (β-GC)." (PMID 35992201, 2022). "The β-glucocerebrosidase 1 (GBA1) gene encodes the lysosomal hydrolase glucocerebrosidase (GCase); recessive mutations in GBA1 cause Gaucher’s disease (GD), and it is now known to be the strongest genetic risk factor for sporadic PD." (PMID 35163450, 2022). "Autosomal recessive variants in Glucosylceramides Beta (GBA1) cause Gaucher disease (GD), the most prevalent lysosomal storage disease." (PMID 35857503, 2022). "Gaucher disease (GD) is an autosomal recessive genetic disease that is caused by GBA1 gene mutations." (PMID 36329499, 2022). "Gaucher disease (GD) is an autosomal recessive disease caused by GBA1 mutations resulting in glucosylceramide accumulation in macrophages." (PMID 36329499, 2022). "Deficient acid β-glucocerebrosidase activity due to biallelic mutations in GBA1 results in Gaucher disease (GD)." (PMID 35628652, 2022). "GBA1 pathogenic variants cause Gaucher disease, a lysosomal storage disorder characterized by the deficiency of the enzyme glucocerebrosidase (GCase)." (PMID 35720097, 2022). "For most GBA1 variants, there is the association with Gaucher disease, an autosomal recessive lysosomal disorder that can manifest in childhood or be present unknowingly in mildly expressing adults and be amenable to treatment." (PMID 36446806, 2022). "Mutations in the GBA1 gene are associated with several neurodegenerative disorders, such as Gaucher disease, Parkinson’s disease, dementia with Lewy bodies, rapid eye movement disorder, and sleep behavior disorders." (PMID 35954187, 2022). "Gaucher disease (GD) is a lysosomal storage disorder resulting from mutations in the GBA1 gene that lead to decreased activity of acid β-glucocerebrosidase (GCase, E.C 3.2.1.45)." (PMID 35628652, 2022). "This additional aspect of the GBA1 gene, namely its association with Gaucher disease, impact on reproductive risk, and potential medical action, requires added time to discuss and creates complexity to risk communication." (PMID 36446806, 2022). "Gaucher disease is caused by biallelic mutations in the GBA1 gene that encodes a lysosomal hydrolase, β-glucocerebrosidase (also known as glucosylceramidase, GBA1)." (PMID 36409725, 2022). "For years, the gold standard for diagnosing Gaucher disease (GD) has been detecting reduced β-glucocerebrosidase (GCase) activity in peripheral blood cells combined with GBA1 mutation analysis." (PMID 35163551, 2022). "Gaucher disease is a lysosomal storage disease, which happens due to mutations in GBA1/Gba1 that encodes the enzyme termed as lysosomal acid β-glucosidase." (PMID 34884512, 2021). "This is best exemplified by mutations in the gene encoding the lysosomal protein GBA1, which causes Gaucher’s disease and has become the most prevalent genetic risk factor for Parkinson’s disease (Do etal, 2019)." (PMID 33851776, 2021). "Both heterozygous carriers of GBA1 variants and people with Gaucher disease have an increased chance of developing Parkinson’s disease." (PMID 34497401, 2021). "Depletion of GCase, typically by homozygous mutations in GBA1, is linked to the lysosomal storage disorder Gaucher’s disease (GD) and distinct or heterozygous mutations in GBA1 are associated with increased Parkinson’s disease (PD) risk." (PMID 34106956, 2021).